TERT (telomerase reverse transcriptase)
Diseases named in the same sentence as TERT in open-access papers (continued):
Sharing a sentence is not in itself a finding about the gene and the disease.
cervical carcinoma (42 papers, 2010 to 2025). A carcinoma arising from either the exocervical squamous epithelium or the endocervical glandular epithelium. "The consistent association of TERT promoter mutations with cervical carcinoma is also supported by the presence of the G to A transition at position −146 in the HPV16-positive SiHa cell line, which is derived from a squamous cell carcinoma of the cervix." (PMID 38033865, 2023). "Distinct profiles of TERT promoter mutations and telomerase expression in head and neck cancer and cervical carcinoma." (PMID 35804458, 2022). "Several cohorts of HPV-driven cancers, namely cervical cancer, head and neck cancers, vulvovaginal cancer, and penile cancer have been reported to harbor hotspot somatic mutations in the TERT promoter." (PMID 36230545, 2022). "However, 95.7% of HPV-positive cervical cancers from an Indian cohort that had poor and moderately differentiated histopathology harbored a TERT promoter mutation, and such mutations also occurred at a higher frequency in cervical tumours from advanced-stage patients." (PMID 36230545, 2022). "The expression of PIF1 can promote cervical cancer cell proliferation and inhibit cell apoptosis by upregulating the expression of telomerase TERT and increasing the rate of the G2/M phase." (PMID 36685888, 2022). "Epigenetic modulation of the TERT promoter is also thought to play a role in TERT induction; hypomethylation of the TERT transcription start site is a common biomarker of cervical cancer, and has been shown to have a functional impact on TERT gene expression." (PMID 36230545, 2022). "In HPV-positive cervical cancer cases TERT gene expression was significantly higher in TERT promoter mutated than in non-mutated tumours regardless of HPV16 E6 levels." (PMID 35804458, 2022). "TERT promoter mutations occurred more frequently in the HPV-negative samples in cancer cohorts that included such cases (i.e., excluding cervical cancer)." (PMID 36230545, 2022). "MIR346 binds to a region in the 3′UTR of TERT mRNA in human cervical cancer cells, leading to an upregulation of TERT expression." (PMID 35408840, 2022). "HeLa cells, an HPV-18-positive cervical cancer cell line, are well studied to clarify the regulatory mechanisms of TERT gene expression." (PMID 34489496, 2021). "For instance, miR-491-5p functions as a tumour suppressor and suppresses cell growth by directly targeting 3’ UTR of TERT mRNA in cervical cancer." (PMID 33802026, 2021). "MIR346 binds to a region in the 3′UTR of TERT mRNA in human cervical cancer cells and astrocytic glioma cells, leading to upregulating TERT expression." (PMID 32680564, 2020). "TERT, overexpressed in cervical cancer cells, determines telomere length and facilitates cancer cells to evade apoptosis and continue proliferation." (PMID 31366565, 2019). "E6 collaborates with the transcription factor c-MYC to upregulate TERT in certain cervical cancer cell lines." (PMID 29045464, 2017). "We identified that TIP60-mediated growth suppression of HPV-induced cervical cancer is mediated in part due to TERT repression through Sp1 acetylation." (PMID 29045464, 2017). "Other studies revealed that using retroviral delivery of siRNAs specific for TERT, successfully inhibited telomerase activity in cervical cancer cell lines." (PMID 23677713, 2013). "TERT resides in 5 p and is affected by aberrant hypermethylation and deregulated expression in cervical cancer, suggesting a target in this region for Magnoid." (PMID 22590557, 2012). "MiRNA-138 suppresses proliferation, migration, and invasion by targeting TERT in cervical cancer." (PMID 39769169, 2024). "In HPV-immortalized cervical cancer cells, overexpression of TERT alters EMT characteristics." (PMID 38278800, 2024). "However, the rarity of recurrent TERT promoter mutations in CIN1-3 and adenocarcinoma of the cervix suggested that this is a late event in the development of cervical cancer." (PMID 38033865, 2023).
cervical carcinoma (continued). "In this study, we used HeLa cells, a human cervical cancer cell line, and observed neither C228T nor C250T mutations in genomic DNA, suggesting that these genetic changes do not occur and contribute to the TERT transcription in HeLa cells." (PMID 34489496, 2021). "Because SP1 acetylation inhibits TERT, cervical cancer growth is inhibited." (PMID 34130593, 2021). "Berberine could downregulate the TERT protein level in the non-small-cell lung cancer cell line, A549, and cervical cancer cell lines, SiHa and HeLa." (PMID 33450878, 2021). "Since HPV infection causes immortalization and TIP60 is destabilized by HPV oncogene E6, we investigated if TIP60 regulates TERT expression, a key factor involved in immortalization, in the context of the HeLa cervical cancer cell line that constitutively expresses the viral oncogenes E6 and E7." (PMID 29045464, 2017). "Notably, although TERT is also a nearby gene, it is not expressed in the uterus tissue; in addition, gene‐based transcriptome‐wide association study (eTWAS) analysis also indicates that TERT expression does not fully explain the GWAS risk loci of cervical cancer (PBonferroni = 0.99)." (PMID 39950845, 2025). "In some cervical cancer biopsies and derived cell lines, the HPV DNA has been shown to integrate near the TERT locus with viral enhancers activating TERT promoter and increased telomerase expression." (PMID 36358677, 2022). "Studies in HeLa cells, a cervical cancer cell line, uncovered the interaction between AGO2 and telomerase reverse transcriptase (TERT), as well as the telomerase RNA component (TERC), which promotes TERT and TERC association." (PMID 33668654, 2021). "Normally, TERT is not expressed or is expressed at low levels in keratinocytes; however, one study found that 64% of cervical cancers displayed high TERT expression." (PMID 36230545, 2022). "In contrast, HDAC inhibitor trichostatin A treatment induced significant expression of TERT mRNA and telomerase activity in somatic cells, while, under the same conditions no altered response was noted with cervical cancer cell lines." (PMID 33802026, 2021). "However, this regulation of TERT by TIP60 is a mechanism that seems to be conserved in cervical cancer cells and is not restricted to only HPV positive cells." (PMID 29045464, 2017). "In addition, PIF1 binds directly to TERT and influences proliferation and apoptosis independent of telomerase activity, although the mechanisms remain unclear in cervical cancer cells." (PMID 38278800, 2024). "C-33A cells, cervical cancer cells without HPV infection, also showed an induction of TERT expression upon TIP60 knockdown." (PMID 29045464, 2017).
ovarian carcinoma (42 papers, 2010 to 2025). A malignant neoplasm originating from the surface ovarian epithelium. "In summary, it can be recommended that ovarian cancer patients should be diagnosed for TERT promoter mutations and should be additionally under adequate follow-up care in the months after chemotherapy." (PMID 37548940, 2024). "For example, self-reported hypothyroidism or myxoedema exhibited a strong association particularly at the TERT locus, which was also exclusively responsible for several subtypes of ovarian cancers." (PMID 32109421, 2020). "In ovarian cancer, TERT promoter mutation and PIK3CA mutation are considered mutually exclusive, whereas this coexistence is reported in other carcinomas." (PMID 29222734, 2018). "Among the genotyped 145 SNPs, 11 SNPs from two genes (TEP1 and TERT) showed significant associations with overall risk of ovarian cancer (P < 0.05 and Q < 0.10)." (PMID 28233473, 2017). "Notably, hypermethylation of the TERT promoter has been strongly associated with gastric, cervical and ovarian cancers." (PMID 40134806, 2025). "However, the detection of mutation in the TERT promoter in early FIGO stages of ovarian cancer patients appears to be a reliable prognostic marker." (PMID 37548940, 2024). "The other SNP that was associated with ovarian cancer risk was TERT: rs2853676." (PMID 28233473, 2017). "A gene variant in the TERT gene has been suggested to be associated with epithelial ovarian cancer." (PMID 27876019, 2016). "The risk allele at rs7705526 has been shown to result in increased TERT promoter activity in luciferase reporter assays conducted in ER-negative breast, ER-positive breast and ovarian cancer cell lines, and was reported to be associated with TERT transcript levels in benign prostate tissue." (PMID 25487306, 2015). "A closer inspection of the TERT locus, encoding a component of telomerase, has uncovered three independent regions of strong association with breast or ovarian cancer that only partially overlap and appear to act through different mechanisms of transcriptional regulation or splicing, respectively." (PMID 24025454, 2013). "However genotypes at TERT rs7726159 were associated with ovarian cancer risk in the smaller, five-study replication study (Pper-allele = 0.03)." (PMID 20628624, 2010). "The variant of TERT gene (rs2242652) which located on 5p15, intron 4 of TERT (encoding telomerase reverse transcriptase), seems to be associated with cancer risk as this SNP has been associated with multiple cancers, including breast, ovarian cancer, and prostate." (PMID 31814184, 2020). "In advanced ovarian cancer, TERT expression is positively correlated with sensitivity to platinum-based chemotherapy." (PMID 39871386, 2025). "In ovarian cancer cells, hypoxia induces predominant active wild type-TERT isoform expression, increasing both TERT and telomerase activity maintaining telomer length." (PMID 32536347, 2020). "Our aim was to investigate the potential role of ATRA as an anticancer drug in a sub-group of ovarian carcinoma where the TERT promoter was hypomethylated." (PMID 31291979, 2019). "Nevertheless, we recently found a hypomethylation of TERT promoter in about one third of serous carcinomas, the most lethal histotype of ovarian cancer." (PMID 31291979, 2019). "The aim of this study was to predict the role of ATRA as a potential anticancer drug in the sub-group of ovarian carcinomas in which the TERT promoter is hypomethylated." (PMID 31291979, 2019). "Our study demonstrated the importance of TERT epigenetic modification in the cellular response of retinoid treatment in ovarian cancer cell lines." (PMID 31291979, 2019). "On the contrary, a study on ovarian cancer reported that a high TERT expression is a predictive factor for the effect of eribulin mesylate." (PMID 29222734, 2018).
ovarian carcinoma (continued). "Using CN data from microarrays, we identified three recurrent regions of CNA where the frequency of alteration appeared to differ between low and late stage HGS ovarian carcinomas (TERT, SKP2 and PRIM2)." (PMID 25916844, 2015). "Candidate gene and genome-wide association studies have identified several SNPs in the TERT-CLPTM1L locus that are associated with cancer risk, and fine mapping has identified rs10069690 as a candidate causal SNP for breast and ovarian cancer risk." (PMID 26053551, 2015). "We tested interactions between 14 TERT-regulatory factors in an ovarian cancer cell line using a screening approach and developed a model to analyse which network interventions were able to silence TERT." (PMID 24550717, 2014). "In this report, we used transfection screening to test interactions among 14 TERT regulatory transcription factors and their respective promoters in ovarian cancer cells." (PMID 24550717, 2014). "Some loci appear to influence both breast and ovarian cancer risk such as BABAM1, TERT, and the protooncogene MYC on chromosome 8q24." (PMID 24025454, 2013). "On day 7 after treatment with 10 MOI of Ad.TERT.LacZ, we observed that ovarian cancer cells had grown well on the layer formed by normal fibroblast cells like being observed in untreated group." (PMID 22623951, 2012). "Ad.TERT.Tβ10-induced apoptosis in primary ovarian cancer cells and immortalized cancer cell lines such as 2774, OVCAR3, and SKOV3, occurred 10- and 48-hours later, respectively." (PMID 22623951, 2012). "Genetic variation at the TERT-CLPTM1L locus at 5p15.33 is associated with susceptibility to several cancers, including epithelial ovarian cancer (EOC)." (PMID 21949822, 2011). "The methylation of TERT is one of the important characteristics of ovarian carcinomas." (PMID 37221474, 2023). "Conversely, the miRNAs located upstream of miR500A act as tumour suppressors since miR532 inhibits the expression of TERT in ovarian cancer, resulting in decreased cell proliferation and lower invasion capacity, and miR188 is down‐regulated in oral squamous cell carcinoma." (PMID 33713376, 2021). "Furthermore, a major study specifically focusing on TERT gene amplification found it to occur in many cancers, such as esophageal, ovarian cancer, and squamous cell carcinoma." (PMID 33329574, 2020). "Likewise, miR-1182, miR-1266, miR-532, miR-1207-5p, and miR-3064 suppress gastric, bladder, ovarian cancer growth and invasion by binding to the TERT 3’UTR." (PMID 33329574, 2020). "In ovarian cancer cells, ectopic expression of TERT could induce epithelial–to-mesenchymal transition (EMT) by up-regulating of Slug." (PMID 31666098, 2019). "If confirmed by further biological and clinical studies, ATRA could be used in combination with platinum therapy in patients with TERT hypomethylated ovarian carcinomas, representing a further example of precision medicine." (PMID 31291979, 2019). "Ovarian carcinomas are heterogeneous tumors with different morphological, molecular and clinical features and are characterized by several aberrantly methylated genes, among which TERT." (PMID 31291979, 2019). "In this study, we examined the effect of ATRA in ovarian cancer cell lines in order to evaluate whether epigenetic modification of TERT promoter gene can be involved in different cellular response to retinoid treatment." (PMID 31291979, 2019). "We previously observed that GSK3 inhibition causes widespread TERT promoter remodelling and that GSK3 inhibited ovarian cancer cells show long-term unstable telomerase suppression, correlating with altered protein expression and oscillation of several TERT regulatory factors, particularly c-Jun." (PMID 24550717, 2014). "Furthermore, X-gal positive cells, indicating β-galactosidase expression by Ad.TERT.LacZ, were detected only in primary ovarian cancer cells." (PMID 22623951, 2012).
ovarian carcinoma (continued). "Although TERT variants have not been previously reported to be associated with ovarian cancer, multiple genome-wide association studies have reported associations with this locus and risk of other cancers." (PMID 20628624, 2010). "Our results demonstrate an inverse correlation between the methylation level of TERT promoter and ATRA efficacy in ovarian carcinoma cell lines." (PMID 31291979, 2019). "By performing Gene set enrichment analysis (GSEA) in the GEO ovarian cancer data set, we found that the RIF1 expression level was positively correlated with TERT-activated gene signatures and TERT downstream PI3K/AKT signaling (GSE7463)." (PMID 30075819, 2018). "This is consistent with observations reported in colon, gastric and ovarian cancer cell types, and with our previous data on the effects of expression of mutant PIK3CA in TERT-NHUC and in other cell types." (PMID 27465249, 2016). "Several ovarian carcinoma cell lines were treated with ATRA, and we determined whether a correlation between the antiproliferative and cytotoxic effects of all-trans retinoid acid and the methylation status of TERT promoter in these cell lines exists." (PMID 31291979, 2019). "Moreover, we intend to answer the question of whether TERT or RIF1 could be established as new biomarkers for the early detection of ovarian cancer regardless of the patient’s age." (PMID 37548940, 2024).